IGF2 (insulin like growth factor 2)
Diseases named in the same sentence as IGF2 in open-access papers (continued):
Sharing a sentence is not in itself a finding about the gene and the disease.
gastric cancer (31 papers, 2005 to 2025). A primary or metastatic malignant neoplasm involving the stomach. "For example, the aberrant methylation of the IGF2/H19 locus results in the overexpression of growth factor IGF2, which has been linked to the progression of colorectal and gastric cancer, as well as Wilms’s tumour and osteosarcoma." (PMID 36982369, 2023). "We examined the status of genomic imprinting of the LIT1, IGF2 and H19 genes in 89 gastric cancers by PCR-restriction fragment length polymorphism (RFLP) analysis." (PMID 19737423, 2009). "IGF2 has also been associated with cell proliferation and differentiation in gastric cancer." (PMID 34452195, 2021). "In this study LIT1, IGF2 and H19 imprinting status in gastric cancer (GC) which is the second most common cause of cancer-related death in the world was investigated and whether LOI of LIT1, IGF2 and H19 are associated with clinicopathological features was evaluated." (PMID 19737423, 2009). "Gastric carcinoma high expressed transcript (GHET1) interacts with IGF2 mRNA binding protein 1 (IGF2BP1), which enhances the interaction between IGF2BP1 and c-Myc and increases the expression of c-Myc, thereby promoting cell proliferation." (PMID 35511773, 2022). "Another study in Korea examined the change in serum IGF1 and IGF2 levels in 20 stomach cancer cases after surgery using blood samples obtained within 10 days before and once after surgery." (PMID 27144430, 2016). "LOI of IGF2 in gastric tumour tissue except from Taiwan in Chinese and in Japanese patients and the clinicopathological features of gastric cancers with LOI of has been reported rarely." (PMID 19737423, 2009). "In this study, we have shown that LOI of the LIT1, IGF2 and H19 are present in 54.6%, 45% and 8.6% of gastric cancer tissues in Chinese patients respectively." (PMID 19737423, 2009). "The study showed LOI of IGF2 is associated with gastric corpus and LNM in gastric cancer tissues, suggesting that IGF2 plays an important role in gastric carcinogenesis." (PMID 19737423, 2009). "IGF2 LOI is present in high frequency in Chinese gastric cancer patients, especially those with gastric corpus cancer." (PMID 19737423, 2009). "The frequency of IGF2 LOI (+) gastric cancers (45%, 18/40) is slightly higher than that reported from Taiwan (34.5%, 10/29)." (PMID 19737423, 2009). "In all, high frequency of IGF2 LOI is present in patients with gastric cancer in the northeast of China." (PMID 19737423, 2009). "Genes associated with lymph node metastasis in human gastric cancer (e.g., Rbp4, Igf2, Fn1) are not significantly upregulated in rats, indicating a lower potential for lymph node metastasis in MNNG-induced rat gastric cancer." (PMID 41211438, 2025). "UCHL3 promotes gastric cancer metastasis by increasing IGF2 expression." (PMID 39605891, 2024). "Therefore, the finding that miR-4521 can repress IGF2 signaling provides a rationale for the treatment of gastric carcinoma with miR-4521." (PMID 33407516, 2021). "The association of IGF2 LOI with lymph node metastasis may contribute to the development and progression of gastric cancer." (PMID 19737423, 2009). "The IGF2 gene may thus play an important role in lymph vessel permeation especially in expanding-type gastric cancers." (PMID 19737423, 2009). "On the other hand, abnormal methylation of genes, for example, IGF2, SLC16A2, SOX11, P2RX7, and MYOD1, were identified in H. pylori infection and significantly correlated with gastric cancer and its clinicopathological features." (PMID 41614769, 2025). "The expression levels of ETS1, IGF2, FOXM1 and E-cadherin were detected by qRT-PCR in the collection of human gastric carcinoma specimens and adjacent normal tissues (cohort A)." (PMID 33407516, 2021). "The positive rate of LIT1, IGF2 and H19 LOI of gastric cancer tissues were 54.6% (12/22), 45% (18/40) and 8.6% (3/32) in Chinese patients." (PMID 19737423, 2009).
gastric cancer (continued). "miR-4521 inhibited by the ETS proto-oncogene 1 (ETS1) targets both insulin = like growth factor 2 (IGF2) and forkhead box M1 (FOXM1) to inhibit Akt/GSK3β/Snai1 pathway proteins, and achieves inhibition of gastric cancer cell metastasis in hypoxia-induced conditions." (PMID 35805066, 2022). "This is the first study to detect on the LOI of LIT1, IGF2 and H19 in gastric cancer in China-Mainland patients and LOI of IGF2 positive correlation with gastric corpus tumour (OR = 8, 95%CI = 1.425-44.920, p = 0.018) and lymph node metastasis (OR = 4.5, 95%CI = 1.084-18.689, p = 0.038)." (PMID 19737423, 2009). "Insulin, insulin-like growth factor 1(IGF1) and insulin-like growth factor 2(IGF2) were the most studied insulin-like peptides (ILPs) regarded as key regulators of energy metabolism and growth, especially IGF1 receptor and IGF2 receptor were expressed in gastric carcinoma cells." (PMID 30299268, 2018).
hepatoblastoma (31 papers, 2000 to 2025). Hepatoblastoma (HB) is a malignant hepatic tumor and is the most common pediatric liver cancer. "A ROC curve analysis of IGF2 was also conducted to evaluate its potential as a diagnostic marker for distinguishing hepatoblastoma patients from healthy individuals." (PMID 40271711, 2025). "IGF2 is a growth factor frequently overexpressed in hepatoblastomas due to loss of imprinting at 11p15 or paternal uniparental disomy at 11p15." (PMID 29228658, 2017). "IGF2, a maternally imprinted foetal growth factor gene, is implicated in many childhood tumours including hepatoblastoma (HB); however, the genetic and epigenetic alterations have not comprehensively been studied." (PMID 19034281, 2008). "Patterns of allele-specific expression of H19 and insulin-like growth factor-2 (IGF-2) were examined in tissue obtained from 30 children diagnosed with hepatoblastoma." (PMID 10732739, 2000). "Additionally, we found that serum IGF2 levels may serve as a diagnostic biomarker for advanced hepatoblastoma patients." (PMID 40271711, 2025). "Our recently developed mouse model of MYC-driven hepatoblastoma showed that tumors express high levels of Igf2 (ranked #1 among the differentially expressed genes), supporting the notion that IGF2 plays an important role in tumorigenesis." (PMID 40684183, 2025). "We found that IGF2 stimulates fibroblasts to secrete collagen 1, which subsequently intensifies hepatoblastoma malignancy through the collagen 1/integrin α1 signaling axis." (PMID 40271711, 2025). "We investigated the impact of cholesterol on tumorigenesis to further elucidate IGF2's role in hepatoblastoma." (PMID 40271711, 2025). "We overexpressed SREBF2 in HepG2 cells to elucidate the role of SREBF2 in IGF2‐driven hepatoblastoma tumorigenesis." (PMID 40271711, 2025). "In summary, single‐cell sequencing showed that malignant HB‐like cells demonstrate an IGF2‐induced self‐sustaining ability in hepatoblastoma." (PMID 40271711, 2025). "Abnormal expression of IGF2, H19, and CDKN1C in hepatoblastoma, driven by imprinting defects and/or loss of heterozygosity at 11p15.5, was first observed nearly three decades ago." (PMID 40684183, 2025). "This suggests that targeting malignant HB‐like cells by inhibiting IGF2‐induced pathways can lead to promising treatments for hepatoblastoma." (PMID 40271711, 2025). "Next, we classified hepatoblastoma patients into two groups based on IGF2 levels: high (≥1000 ng mL−1) and low (<1000 ng mL−1) groups." (PMID 40271711, 2025). "Our findings also demonstrate that IGF2‐induced collagen 1 enhanced hepatoblastoma proliferation and hepatoblast‐related marker expression, indicating its importance in malignant HB‐like cell self‐sustainment." (PMID 40271711, 2025). "IGF2 elevated cholesterol levels in hepatoblastoma cells, which significantly accelerated HB stemness characteristics." (PMID 40271711, 2025). "Statistical analysis of correlations between clinical characteristics and IGF2 levels in serums from hepatoblastoma patients." (PMID 40271711, 2025). "We uncovered a unique IGF2‐related malignant HB‐like cell self‐sustaining ecosystem in primary hepatoblastoma." (PMID 40271711, 2025). "Additionally, serum IGF2 levels may serve as a diagnostic biomarker for advanced hepatoblastoma." (PMID 40271711, 2025). "IGF2 levels above 735.7 ng mL−1 indicated a high probability of hepatoblastoma, with 87.88% sensitivity and 69.70% specificity." (PMID 40271711, 2025). "The role of SREBF2 in IGF2‐induced hepatoblastoma was further investigated by silencing SREBF2 in IGF2‐treated HepG2 cells." (PMID 40271711, 2025). "Patients with PRETEXT III‐IV hepatoblastoma exhibited significantly elevated serum IGF2 levels compared to those with PRETEXT I‐II hepatoblastoma (p = 0.0086)." (PMID 40271711, 2025). "Another noteworthy finding is the alteration of the 11p15.5 locus, which houses the IGF2 gene, observed in a significant proportion of hepatoblastomas." (PMID 38390281, 2024).
hepatoblastoma (continued). "Then we specifically investigated the individual genes that indicate hepatocyte differentiation (Cyp2e1), hepatoblastoma markers (Igf2, Afp, Glul, Krt19) and embryonal hepatoblastoma stem cell markers (Dlk1, Epcam and Gpc3)." (PMID 37414763, 2023). "We show that mosaic 11p15.5 alterations in liver FFPE sections of hepatoblastoma patients display IGF2 overexpression and H19 downregulation together with an alteration of the liver zonation." (PMID 37932266, 2023). "Zhen found that in hepatoblastoma, circHMGCS1 and insulin-like growth factor 2 (IGF2) were significantly upregulated and negatively correlated with the prognosis of patients, which is expected to be the biomarkers for the diagnosis and prognosis." (PMID 37599427, 2023). "The high levels of Igf2 and Afp further verified the hepatoblastoma-like tumors arising from ABC-Myc mice." (PMID 37414763, 2023). "Two HGNET-BCOR samples (P1 and P2) showed expression of IGF2 comparable to that in the hepatoblastoma sample." (PMID 31234291, 2019). "The hypermethylation leading to biallelic expression of IGF2 is seen in a range of tumors, also including hepatoblastoma." (PMID 24373183, 2013). "The overexpression of IGF2 and the reduced expression of H19 would play an important role in tumorigenesis of hepatoblastoma." (PMID 24373183, 2013). "Previous reports have demonstrated that expression of insulin-like growth factor 2 (IGF2) is altered in hepatoblastoma." (PMID 10789725, 2000). "Immunohistochemical (IHC) staining and western blot analysis revealed significantly elevated IGF2 and activated signaling pathway‐related protein levels in hepatoblastoma compared to normal liver tissues, indicating that the IGF2 signaling pathway was activated in malignant HB‐like cells." (PMID 40271711, 2025). "IGF2 has a pivotal role in fetal development and could potentially serve as a biomarker for hepatoblastoma diagnosis." (PMID 40271711, 2025). "This suggests that targeting malignant HB‐like cells by inhibiting the IGF2‐induced pathway could be a promising therapeutic strategy for hepatoblastoma." (PMID 40271711, 2025). "We also evaluated IGF2 levels in the serum of patients with hepatoblastoma." (PMID 40271711, 2025). "Western blot analysis showed the decreased expression of HB‐associated genes like AFP, OCT4, GPC3, and DUSP9 in IGF2 KD HepG2 cells, indicating that decreasing IGF2 could reduce hepatoblastoma stemness." (PMID 40271711, 2025). "Furthermore, IGF2 was shown to stimulate fibroblast 2 cells to secrete collagen 1 to intensify hepatoblastoma malignancy." (PMID 40271711, 2025). "Serum IGF2 expression levels in hepatoblastoma patients were measured using an ELISA assay." (PMID 40271711, 2025). "Notably, the results revealed a significant upregulation of serum IGF2 levels in the hepatoblastoma group." (PMID 40271711, 2025). "The finding that PLAG1 is overexpressed and induces IGF2-p3 activation also in hepatoblastoma cell lines suggests that PLAG1 and PLAGL2 may play a wider role in IGF2 overexpression in cancer." (PMID 37371750, 2023). "We identified high levels of IGF2 in patients enriched for Hepatoblastoma I and Hepatoblastoma II signatures, GATA1 in patients enriched for the Erythroid-like signature, POSTN in patients enriched for the DCN-high signature, and CHGA in patient 8 who was enriched in the Neuroendocrine signature." (PMID 36008377, 2022). "Hepatoblastoma development has been associated with UPD (4.7%, P < 0.001) although it is also observed in patients with KCNQ1OT1:TSS-DMR-LOM (0.7%) and H19/IGF2:IG-DMR -GOM (0.8%, P < 0.001)." (PMID 33101381, 2020). "Taken together, these observations suggest that the oncogenic activities of PLAG1 is at least partly mediated by IGF2 signaling and that IGF2 signaling is a potential therapeutic target in pleomorphic adenoma and hepatoblastoma and possibly also in lipoblastoma." (PMID 31426421, 2019).
hepatoblastoma (continued). "The Western blot analysis of IGF2‐treated cells demonstrated increased activation of the IGF2‐related signaling pathway and the increased expression of HB‐associated proteins, including AFP, OCT4, GPC3, DUSP9, and cMYC, indicating IGF2's role in sustaining hepatoblastoma stemness." (PMID 40271711, 2025). "Additionally, post‐treatment hepatoblastoma patients displayed reduced IGF2 levels compared to their pre‐treatment counterparts, indicating that serum IGF2 levels could potentially serve as a biomarker for treatment response." (PMID 40271711, 2025). "We first performed a transcriptomic evaluation of the two well‐recognized hepatoblastoma cell lines, HepG2 and HUH6, using Pearson's analysis with gene signatures in the public GSE168997 dataset to elucidate IGF2′′s role in hepatoblastoma (AFP, DUSP9, GPC3, DLK1, MYC, EPCAM, KRT8, and LIN28B)." (PMID 40271711, 2025). "Additionally, we simultaneously detected the expression levels of IGF2, SREBF2, DUSP9, and LDs in consecutive sections of 16 hepatoblastoma patient tissues." (PMID 40271711, 2025).
depression (30 papers, 2011 to 2025). "IGF2 is implicated in the pathophysiology of a number of mental illnesses, including anxiety and depression." (PMID 40457890, 2025). "A decrease in IGF2 hippocampal expression is significantly associated to depression-like behavior induced through chronic restraint stress." (PMID 30804991, 2019). "IGF2 is implicated in behavioral phenotypes such as fear extinction, depression, and memory consolidation and enhancement in rodents." (PMID 27083047, 2016). "Knocking out IGF2 reduces ketamine’s behavioral antidepressant effect, and mice resilient to induced depression show higher amounts of IGF2 than mice that were susceptible to depression paradigms." (PMID 35546951, 2022). "In the current study, we assessed whether maternal mental health during pregnancy (depression, anxiety and perceived stress) was associated with cord blood methylation, focusing on the IGF2/H19 ICR, one of the key imprinted loci, and IGF2 DMR0." (PMID 27023171, 2016). "We found that serum IGF-2 levels were significantly lower in both the mania and depression subgroups when compared to healthy individuals." (PMID 38563028, 2024). "We found that serum IGF-2 levels were much lower in both the mania and depression subgroups than those in healthy controls (mania: 67.19 ± 21.52 ng/ml, depression: 63.43 ± 20.67 ng/ml, controls: 88.72 ± 31.55 ng/ml; H = 29.692, P < 0.001)." (PMID 38563028, 2024). "For PD, a bioinformatics study indicated that IGF2 was intersected between PD and Major depressive disorder." (PMID 37051594, 2023). "Nonetheless, it has been recently shown that IGF-2 intrahippocampal injections not only alleviate depression-like behaviors in both rat and mice models, but also enhance memory consolidation in rats." (PMID 37894932, 2023). "The neuropeptides adrenomedullin, insulin-like growth factor 2, prodynorphin, and resistin were identified as mutually expressed in both periodontitis and depression, also playing a role in identifying depression." (PMID 37396968, 2023). "On the contrary, in the last few decades, IGF-1 has received far more attention than IGF-2 in the context of depression." (PMID 37894932, 2023). "Similar to IGF2, expression of p11 is reduced in the hippocampus of patients suffering from depression as well as in disease-relevant animal models." (PMID 31554266, 2019). "As confirmed by qPCR, two of the upregulated genes were p11 and IGF2, which have both been suggested to be involved in the pathology of depression and the therapeutic response of market drugs on the other hand." (PMID 31554266, 2019). "It was found that highly variable probes in depression-discordant MZ pairs were located in genes within enriched biological pathways and previously associated with depression, such as CACNA1C, IGF2 and MAPK11." (PMID 25918994, 2015). "Expressions of SOD1, CAT, IGF2 and IGF2R also decreased in the postmortem brain regions of individuals with AD and depression compared those of AD, suggesting that the stress-related disorder of depression is indeed a risk factor for AD and exaggerates OS." (PMID 38338968, 2024). "In addition, variable methylation of the Igf2 gene has also been found to be related to the clinical manifestation of depression in monozygotic twins." (PMID 38563028, 2024). "The gene expression of Igf2 was found to be downregulated in the hippocampus in a rat model of depression, and intrahippocampal injection of IGF-2 could mitigate depressive-like behaviors in both rats and mice models." (PMID 38563028, 2024). "Additionally, IGF2 influences various brain functions including memory, depression, and autism and impacts the expression of BDNF." (PMID 39319049, 2024). "Methylation analyses of 9 promoter/regulatory regions of genes known to be implicated in depression/PTSD (ADCYAP1, BDNF, CRHR1, DRD2, IGF2, LSD1/KDM1A, NR3C1, OXTR, SLC6A4) were performed on DNA from blood samples by the MassARRAY EpiTYPER platform, with MassCleave settings." (PMID 36001138, 2023).